LINC00667 (long independently transcribed non-coding RNA 667)
Synonyms: lncOCMRL1
Gene: Long non-coding RNA gene on chromosome 18 (5,237,826 to 5,290,609, forward strand). Ensembl gene ENSG00000263753.
Diseases named in the same sentence as LINC00667 in open-access papers:
LINC00667 is named in the same sentence as 16 diseases in open-access papers, as found by Europe PMC text mining. Sharing a sentence is not in itself a finding about the gene and the disease. The quoted sentences say what the papers report.
breast carcinoma (4 papers, 2019 to 2024). "First, downregulation of LINC00470, LINC00526, and LINC00667 genes in MCF-7 cell lines (breast cancer) was associated with sensitivity to doxorubicin." (PMID 38540157, 2024). "Only high expression of LINC01128, CCDC18-AS1, SH3BP5-AS1, HOTAIRM1, LINC01140, SGMS1-AS1, LINC01578 or LINC00667 had favorable prognosis in breast cancer." (PMID 34828282, 2021). "We found that in the regulatory network, miR-301a-3p, miR-93-5p, miR-454-3p, miR-181b-5p, XIST, LINC00472, MIR31HG, MEG3, MIR155HG, and LINC00667 have been reported in breast cancer." (PMID 34220926, 2021). "MiR-200c-3p, miR-204-5p, miR-20b-5p, miR-7-1-3p, miR-105-5p, miR-342-3p, DNMBP-AS1, HPN-AS1, LINC00461, LINC00472, LINC00667, LOC100128164, LOC284578, MESTIT1, RHPN1-AS1, and SLC26A4-AS1 were significantly associated with breast cancer patients’ overall survival (log-rank P < 0.05)." (PMID 34220926, 2021). "The downregulation of gene expression is characteristic for LINC00667 in the papillary subtype of bladder cancer, LINC00667 in basal-like and HER2 breast cancer, and LINC00667 in colorectal adenocarcinoma with high microsatellite instability." (PMID 38540157, 2024).
glioma (3 papers, 2020). A benign or malignant brain and spinal cord tumor that arises from glial cells (astrocytes, oligodendrocytes, ependymal cells). "For instance, LINC00667 facilitates the formation of glioma vasculogenic mimicry and the level of LINC00667 is positively associated with the development of glioma." (PMID 33569351, 2020). "The roles of LINC00667 in cancer development have been explored in glioma, hepatocellular carcinoma and non-small cell lung cancer, but not in nasopharyngeal carcinoma (NPC)." (PMID 33569351, 2020). "As was reported earlier, SNHG16 and linc00667 are increased in gliomas, which enhances cell VM formation ability." (PMID 32368853, 2020).
colorectal cancer (2 papers, 2020 to 2021). A primary or metastatic malignant neoplasm that affects the colon or rectum. "It has been reported that LncRNA LINC00667 is upregulated in many kinds of cancers such as colorectal cancer and lung cancer as well as nasopharyngeal carcinoma." (PMID 34907204, 2021).
hepatocellular carcinoma (2 papers, 2020 to 2023). A malignant tumor that arises from hepatocytes. "Besides, LINC00667 contributes to the malignant progression of nephroblastoma, hepatocellular carcinoma (HCC), and cholangiocarcinoma." (PMID 37827696, 2023).
renal fibrosis (2 papers, 2021 to 2022). A final common manifestation of a wide variety of chronic kidney diseases characterized by glomerulosclerosis and tubulointerstitial fibrosis. "Reducing LINC00667 also promotes renal tubular epithelial cell proliferation and ameliorates renal fibrosis via the miR-19b-3p/LINC00667/connective tissue growth factor signaling pathway." (PMID 36299256, 2022). "A further mechanistic study has revealed that LINC00667 promotes renal fibrosis by regulating the miR-19b-3p/LINC00667/CTGF signaling pathway." (PMID 34054586, 2021).
cholangiocarcinoma (1 paper, 2021). A carcinoma that arises from the intrahepatic biliary tree (intrahepatic cholangiocarcinoma) or from the junction, or adjacent to the junction, of the right and left hepatic ducts (hilar cholangiocarcinoma). "Also, YY1 had been shown to be involved in various tumors progression and associated with adverse clinical prognosis in tumor patients, for instance, YY1 stimulated LINC00667 transcription that enhanced the proliferation of cholangiocarcinoma." (PMID 34898474, 2021).
esophageal cancer (1 paper, 2023). A primary or metastatic malignant neoplasm involving the esophagus. "For instance, LINC00667 stimulates migration, invasion, and proliferation in cells pertaining to esophageal cancer by mediating the sponge axis miR-200b-3p/SLC2A3." (PMID 37827696, 2023).
non-small cell lung carcinoma (1 paper, 2020). A group of at least three distinct histological types of lung cancer, including non-small cell squamous cell carcinoma, adenocarcinoma, and large cell carcinoma. "Moreover, overexpression of LINC00667 is strongly correlated with overall survival of patients with non-small cell lung cancer (NSCLC)." (PMID 33569351, 2020).
periodontitis (1 paper, 2022). An acute or chronic inflammatory process that affects the tissues that surround and support the teeth. "A number of other long non-coding RNAs, namely Linc0116, Linc00667, CDK6-AS1, FENDRR and DIRC3 have been found to be down-regulated in the blood samples of patients with periodontitis." (PMID 36456933, 2022).
thymoma (1 paper, 2024). A neoplasm arising from the epithelial cells of the thymus. "Upregulation of LINC00668 gene occurs in COAD, READ, STAD, and LUSC, of LINC00526 and LINC00667 genes occurs in thymoma (THYM), and of LINC01443 gene occurs in skin cutaneous melanoma (SKCM)." (PMID 38540157, 2024). "LINC00526 and LINC00667 genes are co-expressed with genes participating in the processing of capped intron-containing pre-mRNA, RNA processing, and transcriptional and post-transcriptional regulation of gene expression in thymoma." (PMID 38540157, 2024).
cancer (6 papers, 2019 to 2024). A tumor composed of atypical neoplastic, often pleomorphic cells that invade other tissues. "The potential for participation in cancer-associated processes decreases in a set of LINC00667, LINC00668 > LINC00470 > LINC01926, LINC01544, LINC01909, depending on the number of functional terms." (PMID 38540157, 2024). "High expression of LINC00667 can promote cancer cell proliferation, migration and accelerate cell cycle." (PMID 37901333, 2023). "Thus, LINC00526 and LINC00667 are represented in the majority of pathways in different cancer types." (PMID 38540157, 2024). "Among them, aberrant expression of SNHG14 and SNHG15 have been discovered in cancers, expression of LINC00667 was proved as a biomarker to predict relapse free survival in patients with small hepatocellular carcinoma, most recently, the roles of VLDLR-AS1 and TNRC6C-AS1 in PTC have been studied." (PMID 31372094, 2019). "In addition, LINC00667 positively regulates KIAA1429 through sponging miR-556-5p, thus forming a positive feedback loop and promoting cancer progression." (PMID 37901333, 2023).
tumor (6 papers, 2020 to 2024). "As a result, LINC00667 overexpression significantly advanced the growth of tumor volume and mass versus the NC group." (PMID 37827696, 2023). "The RT-qPCR data revealed that the expression of LINC00667 was remarkably lower in tumor tissue obtained from the sh-LINC00667 group compared to the control group." (PMID 34907204, 2021). "The tumor volume curve and tumor weight showed that LINC00667 knockdown significantly reduced the growth of HCC tumor in mice." (PMID 34907204, 2021). "This indicates LINC00667 functions as a tumor promotor in promoting HCC progression through targeting miR-130a-3p/AR axis, making a novel biomarker and potential therapeutic target for HCC." (PMID 34907204, 2021). "Thus, overexpressing LINC00667 accelerated ccRCC cell growth in an in-vivo xenograft tumor model." (PMID 37827696, 2023). "These molecular data are consistent with the findings of lymph node invasion, tumor size and OS of HCC patients, which imply that LINC00667, as a promoting factor, can enhance CP, CM, and CI in HCC cells." (PMID 34907204, 2021). "We found that LINC00667 expression was highly correlated with several clinicopathological characteristics of 63 HCC tissues, namely, tumor size, TNM-stage, T grade and lymph node invasion." (PMID 34907204, 2021). "Therefore, miRNA-130a-3p can serve as a tumor inhibitory factor of HCC, and LINC00667 probably regulates the biological behavior of HCC through sponging miRNA-130a-3p." (PMID 34907204, 2021).
LINC00667 also shares sentences with these, for which no sentence is quoted: nasopharyngeal carcinoma (2 papers); lung carcinoma (1); oral squamous cell carcinoma (1); testicular germ cell tumor (1).